Y_RNA (Y RNA )
Gene: Miscellaneous RNA gene on chromosome 1 (197,685,640 to 197,685,740, reverse strand). Ensembl gene ENSG00000207139.
Homologues: Orthologues: chimpanzee Y_RNA (100% identical), macaque Y_RNA (96% identical), guinea pig Y_RNA (86% identical). Paralogues in human: RNY3 (86% identical), Y_RNA (85% identical), Y_RNA (84% identical), Y_RNA (83% identical), RNY3P1 (82% identical), Y_RNA (82% identical), RNY3P9 (81% identical), Y_RNA (81% identical), RNY3P5 (80% identical), Y_RNA (80% identical), RNY3P16 (79% identical), RNY3P7 (79% identical), and 91 more.